CAV1 (caveolin 1)
Diseases named in the same sentence as CAV1 in open-access papers (continued):
Sharing a sentence is not in itself a finding about the gene and the disease.
cancer (continued). "In conclusion, CAV1 promotes the Warburg effect and ROS production, which inhibits PTP1B to augment CAV1 phosphorylation on tyrosine-14, thereby increasing the metastatic potential of cancer cells." (PMID 35740528, 2022). "Expression of K176R mutant CAV1 resulted in increased transport activity of P-gp and reduced the effectiveness of cytotoxic drugs in cancer cell lines." (PMID 35158857, 2022). "Here we demonstrated that 2-DG treatment reduces CAV1-enhanced migration and metastasis, corroborating the relevance of CAV1-induced metabolic reprogramming in determining the metastatic potential of cancer cells." (PMID 35740528, 2022). "The CAV1-dependent metabolic coupling between stromal and cancer cells, finally achieving a stromal cell support of ‘energetic’ metabolites for the generation of further ATP in cancer cells is supposed to occur via the so-called exosomes." (PMID 35155239, 2022). "Along the same line, CAV1 was identified as a specific marker of epithelial to mesenchymal transition (EMT) across cancer cell lines." (PMID 35962130, 2022). "For the ESCRT independent pathway, both caveolin-1, flotillins, and Rab31 are ubiquitously overexpressed in cancer and promote cancer progression and chemoresistance by their function in controlling exosomes secretion." (PMID 36320056, 2022). "A clinicopathological study demonstrated that patients with Cav-1+ CAFs had significantly higher rates of vascular and pleural invasion than those with Cav-1− CAFs, and a similar correlation was exhibited by Cav-1+ cancer cells." (PMID 36422541, 2022). "For example, the morphology and proliferation of cancer cells can actually become insensitive to ECM stiffness through regulation of caveolin-1 (Cav1), a scaffold protein essential for integrin-mediated mechanotransduction." (PMID 35631616, 2022). "We observed an increase in lactate production upon PTP1B inhibition (respectively), indicating that PTP1B regulates cancer cell metabolism by controlling CAV1 phosphorylation." (PMID 35740528, 2022). "Previous studies have reported that CAV1 can facilitate the activation of canonical Wnt signaling pathway in a variety of cancers." (PMID 35000526, 2022). "Although its role in cancer has been a long-standing controversial topic, caveolin-1 (Cav-1) has established its importance in almost every cancer-related theme." (PMID 35954304, 2022). "Challenges remain in elucidating the role of CAV1 in the TME comprised of several distinct cell types, including immune cells, cancer-associated fibroblasts (CAF), endothelial cells, and adipocytes with different functions." (PMID 35660849, 2022). "A mechanism based on miRNA has also been described for ovarian cancer; in this case, the resistance of cancer cells to paclitaxel is mediated by exosomes containing miR-1246, which can target caveolin 1, i.e., a regulator of P-gp expression." (PMID 35629286, 2022). "By leveraging patient and cell line datasets, we uncover a molecular link between PrPC and CAV1 across cancer." (PMID 35962130, 2022). "As mentioned, our results here demonstrate that the elevated expression of CAV1 reduces mitochondrial respiration in cancer cells." (PMID 35740528, 2022). "This protein, as a ligand of the sonic hedgehog pathway – similar to CyR61 and Caveolin-1 – is also involved in the stimulation of cancer cell proliferation and migration." (PMID 36113340, 2022). "An increased expression of CAV-1 on malignant epithelial cells and the loss of stromal CAV-1 expression on cancer-associated fibroblasts are important indicators of disease progression and unfavorable clinical outcomes in solid tumors." (PMID 36556936, 2022). "Recent research has shown that after short-time anticancer drug treatment, the CAV1 expression was increased in cancer cells, which resulted in the enhanced migration and invasion of cancer cells in vivo." (PMID 36354566, 2022). "Rescued CAV1 expression levels within stromal fibroblasts in turn inhibited the cancer cells metabolism." (PMID 35155239, 2022).
cancer (continued). "Cav1 represses the activation of unfolded protein response, attenuating PERK/IRE1α signaling and increasing susceptibility to ER stress and hypoxia in cancer cells." (PMID 36187764, 2022). "The promoter methylation of the CAV-1 gene results in CAV-1 silence, fostering cancer cell proliferation." (PMID 35682652, 2022). "Caveolin-1 (CAV1) is a scaffolding protein that promotes cancer cell migration, invasion, and metastasis in a manner dependent on CAV1 phosphorylation on tyrosine-14 (pY14)." (PMID 35740528, 2022). "Similar to CAV1, genetic alterations of CAVIN1 in human cancers are rare, represented by less than 2% mutations and amplifications." (PMID 35158857, 2022). "EGFR, KIT, MET, PPARG, and STAT5A were enriched in the Pathways in cancer, CAV1, EGFR, and MET were enriched in the Proteoglycans in cancer, and MET and PPARG were enriched in the Transcriptional misregulation in cancer." (PMID 35063044, 2022). "According to the Cancer Genome Atlas Program (TCGA) of human cancers, the amplification of the CAV1 locus is infrequent (<2%)." (PMID 35158857, 2022). "While CAV1-dependent endocytosis enhances cancer cells’ chemosensitivity to TDM125, others have shown a role for caveolae-mediated endocytosis in TDM1 resistance." (PMID 35534471, 2022). "During the cancer process, cancer cells experience oxidative stress, which enhances HIF-1α expression and stimulates TGF-α and Caveolin (Cav1) protein loss, downregulating TGF-α; moreover, stromal cells undergo autophagy and become CAFs." (PMID 36059650, 2022). "Recently, the role of CAV1 in cancer prognosis and therapy resistance, including chemo- and radiotherapy, has been reviewed." (PMID 35158857, 2022). "For the MDA-MB-231, cancer cells which express CAV1 endogenously, CAV1 levels were reduced using a specific short hairpin construct." (PMID 35740528, 2022). "To further investigate by which pathway cancer cells absorb exosomes, we knocked down Caveolin-1 and Clathrin in PC9 cells using three shRNAs, respectively." (PMID 33461557, 2021). "In parallel, a cancer-associated fibroblast (CAF) signature was anchored by FAP, CAV1, VIM, and additional genes." (PMID 34518533, 2021). "A characteristic shift in epithelial-stromal CAV1, as known for many other cancer entities during cancer development and progression, was established here for penile SCC." (PMID 33868995, 2021). "Loss of stromal caveolin-1 (Cav-1) is a biomarker of a cancer-associated fibroblast (CAF) phenotype and is related to progression, metastasis, and poor outcomes in several cancers." (PMID 34813586, 2021). "The Cav-1/AKT/mTOR axis has been shown to promote the proliferation of cancer cells and vascular metastasis." (PMID 34955837, 2021). "The role of AREG, STAG3, CAV1 and C19orf57 in cancer were analyzed through Gene set enrichment analysis (GSEA)." (PMID 33712015, 2021). "Various types of human cancers were characterized by an altered expression of epithelial or stromal caveolin-1 (CAV1)." (PMID 33868995, 2021). "Hypoxia regulates membrane protein endocytosis through a Cav-1-mediated process in some cancer cell lines." (PMID 34490102, 2021). "CAV1 is the chief component of the caveolae plasma membranes in most human cells and participates in immune response and cancer progression." (PMID 35127724, 2021). "Our work has important implications not only in the understanding of Kv1.3-dependent cancer progression but possibly also in metabolic diseases, where Cav1 and Kv1.3 both play an important role." (PMID 34196606, 2021). "In advanced stages of cancer, we observed areas with strong CAV1 staining, indicating its high expression, especially in cancer cells invading neighboring stroma." (PMID 35008571, 2021). "We found the CAV1 expression is significantly decreased in 9 of the 15 cancer types, which contain enough data for this kind of analysis." (PMID 34786475, 2021).
cancer (continued). "CAV1 is a resident protein of caveolae, which is a special type of lipid rafts required for the assembly and function of invadopodia in cancer cells." (PMID 34136381, 2021). "CAV1-expression was significantly higher in cancer cells of CP (82%) than in the other patterns (0%; p < 0.001)." (PMID 33672734, 2021). "Taking various cancers into account, CAV1 was found to be downregulated in some while increased expression seen in a few others, indicative of a biphasic nature of CAV149." (PMID 33739025, 2021). "Although Cav-1 participates in the metabolism of cancer cells and regulates the survival of cancer cells, the relationship between Cav-1 and RCC merits in-depth study." (PMID 34955837, 2021). "Cav-1 was shown to be highly expressed in many tumors and such a high protein level was correlated with cancer invasion, metastasis, and poor survival." (PMID 33920031, 2021). "The mutually exclusive CAV1-expression in cancer cells and stroma observed in this study has been described previously but remains as yet unexplained." (PMID 33672734, 2021). "CAV1, delivered by cancer cell-derived exosomes and its accumulation in OSCC TME promoted EMT and trans-differentiation of fibroblasts junto CAF's23." (PMID 33739025, 2021). "In contrast, CP administration decreased Cav-1 to subsequently promoted the ubiquitination-activated proteasome degradation of β-catenin, resulting in the suppression of cancer metastasis." (PMID 34168559, 2021). "Caveolin-1 (CAV1) can be expressed by both cancer cells and cancer-associated fibroblasts (CAFs) and has multifarious effects, including the promotion of proliferation, invasion and chemoresistance." (PMID 33672734, 2021). "Our data increases the understanding of the heterogeneity of cancer by consolidating the roles of Kv1.3 and Cav1 as targets for anti-cancer therapies." (PMID 34196606, 2021). "Although potentially protective in bourgeoning tumors, higher levels of either Caveolin-1 mRNA or protein have been reported in varying cancers strongly correlating with poor survival in advanced cancer patients." (PMID 33718218, 2021). "As known from other cancer entities, epithelial-stromal CAV1 expression levels have the potential to serve as novel biomarker to monitor cancer progression and even therapy resistance." (PMID 33868995, 2021). "Cav1 acts either as a tumor suppressor or as an oncogene, depending on the cancer type and the clinical stage of the disease." (PMID 34196606, 2021). "In the past, human studies extensively focused on the role of Cav-1 in epithelial cancer cells reporting a significant increase in Cav-1 expression in malignant lesions than benign breast tissue." (PMID 33531603, 2021). "As certain integrins including integrins αv and β3 were shown to associate with progression and anchorage-independent growth of cancers, we investigated the effect of artocarpin on altering the pattern of the integrins as well as the Cav-1 expressions." (PMID 33920031, 2021). "For comparison, the normal tongue epithelium showed some level of CAV1 expression, but at a much lower level than in cancer tissues." (PMID 35008571, 2021). "The high expression levels of both catulin and CAV1 proteins were visible in streams/clusters of cancer cells invading the stroma." (PMID 35008571, 2021). "In HCC with HBx truncated at C-terminus (HBxΔC), Cav-1 was upregulated at the transcriptional level, thereby promoting cancer aggressiveness via the LRP6/β-catenin/FRMD5 signaling axis." (PMID 34168559, 2021). "The scaffolding protein Cav-1 was shown to have an impact on behaviors of cancer cells, including cell movement and anoikis resistance." (PMID 33920031, 2021).
cancer (continued). "This suppressor status has been challenged over time, however, with some limited but fairly consistent evidence of Cav-1 overexpression in various types of cancer." (PMID 33195223, 2020). "At the molecular level, CAV1 is viewed as a negative regulator of various pathways relevant to cell proliferation and survival due to inhibitory interactions with cancer-relevant signaling proteins." (PMID 32811828, 2020). "In an opposite manner, cancer cells with mitochondrially localized CAV1 are more resistant to ER stress, have a more stable mitochondrial membrane potential, and have increased mitochondrial biogenesis and cell survival." (PMID 32458269, 2020). "CAV1 rs3807987 and rs7804372 are located in introns, but intron polymorphisms may influence CAV1 expression levels and protein function by compounding with nearby polymorphisms, alternative splicing, and affecting the stability of mRNA during the progression of the cancer." (PMID 32243098, 2020). "Taken together, these results strongly indicate that CAV1 presence in different cancer cells reduces HIF1α activity and concomitantly target gene expression in hypoxia." (PMID 32825247, 2020). "Caveolin-1 (CAV1) enhanced migration, invasion, and metastasis of cancer cells is inhibited by co-expression of the glycoprotein E-cadherin." (PMID 32152405, 2020). "Caveolae are caveolin-1- (Cav-1-) enriched subdomains in the plasma membrane that are deregulated in cancer cells and contain a high cholesterol and sphingolipid content." (PMID 32377291, 2020). "Cav-1 is a caveola-forming membranous protein comprised of 178 amino acids, and plays a dual role as a promoter and a suppressor depending on varying cancer types and stages." (PMID 33381039, 2020). "CAV1 impairs DLP-1 activation by PKA at the mitochondrial level in cancer cells, which generates mitochondrial instability and dysfunction." (PMID 32458269, 2020). "Bailey and Liu demonstrated that caveolin-1 expression was upregulated during the epithelial-to-mesenchymal transition; furthermore, once expressed, caveolin-1 greatly increased cancer cell adhesion." (PMID 32676485, 2020). "Taken together, these findings suggest that CAV1 reduces HIF transcriptional activity in hypoxia in human cancer cell lines of diverse origin." (PMID 32825247, 2020). "Alternatively, EGF treatment induces caveola-dependent endocytosis of plasma membrane E-cadherin/β-catenin complex, disrupts cell–cell contacts, downregulates E-cadherin as well as CAV1, and thereby promotes invasion of cancer cells." (PMID 32458269, 2020). "The mechanism of action of the new molecule involves Caveolin-1 overexpression and actin cytoskeleton disorganization in the cancer cells." (PMID 33353176, 2020). "Cav-1 encodes a 22 kDa protein and is located at chr7q31.1, a fragile genomic region also termed as FRA7G and is often deleted in cancers." (PMID 31901898, 2020). "In contrast, emerging evidence shows that Cav-1 is a potential oxidative stress-related target during oxidative stress-induced cancer initiation and development." (PMID 31919341, 2020). "Growing evidences have shown that upregulation of Cav-1 was found in multiple drug-resistance cancer cells." (PMID 32117718, 2020). "This study explores the potential impact of differential CAV1 levels in EC on the acid sphingomyelinase (ASMase)/ceramide pathway as a key player in the regulation of EC apoptosis upon irradiation and cancer cell radioresistance." (PMID 32273493, 2020). "The discovery of new communication patterns between cancer and stromal cells, in which Cav-1 seems to be an important key note for both sides, prompted a new paradigm for prognosis of certain cancer types, based on evaluation of Cav-1 in stromal cells." (PMID 33195223, 2020). "The interaction of CAV1 with antidiabetic drugs has been mainly investigated in the context of different types of cancers." (PMID 32082483, 2020).
cancer (continued). "More recently, studies by Liu and coworkers demonstrated that knockdown of CAV-1 in A549 cells enhanced cisplatin-triggered cancer death." (PMID 32733649, 2020). "In CRC, co-culture of fibroblasts and cancer cells resulted in an upregulation of oxidative stress-related enzymes and autophagy genes and the downregulation of CAV1 in fibroblasts that in turn promoted cancer cell proliferation." (PMID 32760726, 2020). "The contributions of these intracellular pools to CAV1 function are generally less well understood, and this is also the case in the context of cancer." (PMID 32458269, 2020). "On the other hand, CAV1 acts as a promoter of metastasis in later stages of cancer, where enhanced expression of CAV1 favors the malignant phenotype and correlates with an increase in cell migration, metastasis, and multidrug resistance." (PMID 32152405, 2020). "Recent studies from our laboratory indicate that not only the expression of CAV1 at the plasma membrane but also the phosphorylation of CAV1 on tyrosine 14 is necessary to increase the metastatic potential of cancer cells in vitro and in vivo." (PMID 32458269, 2020). "The expression levels of CAV1 protein in stromal cells and ATG4C protein in cancer cells are significantly associated with histologic subtypes of EOC." (PMID 32401768, 2020). "The expression of CAV1 is higher in cancer compared to benign tissue and correlates with poor prognosis." (PMID 32458269, 2020). "Further, CAV1 is involved in diverse cellular processes including signal transduction, cell cycle, proliferation, apoptosis, cancer cell invasion, migration and metastasis." (PMID 32401768, 2020). "Cav-1 is thought to be related to the regulation of many biological processes in both normal tissues and cancer." (PMID 32377291, 2020). "Our results also revealed that CAV1 protein level in the stroma, ATG4C protein level in cancer cells, and high expression of both CAV1 and ATG4C proteins in the stroma were related to histologic subtypes of EOC." (PMID 32401768, 2020). "Numerous studies have indicated that the role of caveolin-1 expression depends on the cell type and the stage of the cancer in question." (PMID 32676485, 2020). "The authors suggest that targeted therapy against CAV1 should aid in re-establishing autophagy and thereby serve to treat this type of cancer." (PMID 32458269, 2020). "Our study also showed a positive association between CAV1 and ATG4C protein expression in cancer cells and stromal cells separately." (PMID 32401768, 2020). "Caveolin-1, an essential constituent of plasma membrane invaginations called caveolae, is known to be involved in cancer progression and angiogenesis." (PMID 32676485, 2020). "We found that SA inhibited Cav-1 expression levels in a dose- and interval-dependent way for both cancer cells." (PMID 33381039, 2020). "Recent studies have shown that caveolin-1 plays a key biological role in cancer-related processes, including tumor metastasis and angiogenesis." (PMID 32926104, 2020). "On the other hand, CAV1 overexpression inhibits ER-mitochondria communication and remodeling upon ER stress in cancer cells, such as HeLa cells overexpressing CAV1 or MDA-MB-231 cells with high endogenous levels of CAV1." (PMID 32458269, 2020). "The MDA-MB-435 cancer cell line expresses very low levels of Cav1 and few caveolae, and herein serves as host for stable expression of wild-type, phosphomimetic Y14D and non-phosphorylatable Y14F Cav1 mutants." (PMID 31803361, 2019). "Different mechanisms are summarized illustrating how CAV1 promotes such traits upon expression in cancer cells (intrinsic mechanisms)." (PMID 31362353, 2019). "CAV1 expression is known to be reduced in a number of human cancers, such as lung, mammary, colon, as well as ovarian, sarcoma, including osteosarcoma, and glioblastoma." (PMID 31362353, 2019).